TNF (tumor necrosis factor)
Diseases named in the same sentence as TNF in open-access papers (continued):
Sharing a sentence is not in itself a finding about the gene and the disease.
chlamydial infection (continued). "Collectively, these disparate observations emphasize the need for a detailed evaluation of the role of TNF-α in clearance of genital chlamydial infections." (PMID 23483844, 2013). "In the C3−/− mice the lung tissue concentrations of IFN-γ and TNF-α, two key cytokines in the defense against chlamydia, and of IL-6 and IL-10, were either similar to or even higher than for WT controls." (PMID 23189195, 2012). "We found that chlamydial infection alters the morphology of monocytes and trigger the release of pro-inflammatory cytokines TNF-α, IL-8, IL-1β and IL-6." (PMID 21249123, 2011). "Further upon chlamydial infection, mononuclear cells are triggered to release a number of proinflammatory cytokines including TNF-α, IL-1, IL-6 and IL-8 and many studies have reported association between cytokine profiles and immunopathogenic mechanisms." (PMID 18828896, 2008). "Chlamydial infection activates a cytokine response including basic fibroblast growth factor by smooth muscle cells, and TNF-α secretion by monocytes." (PMID 18021431, 2007). "Additionally, chlamydia-specific T cells produce tumor necrosis factor-α (TNFα), which further inhibits chlamydial infection by activating oxidative pathways in epithelial cells and phagocytes, and by stimulating adaptive T cell responses." (PMID 40309355, 2025). "Chlamydial infection induces the release of pro-inflammatory cytokines, such as interleukin (IL)-6 and tumour necrosis factor-alpha (TNF-α), and activates the innate immune response, which subsequently amplifies inflammation, particularly in patients with IVIG-unresponsive KD." (PMID 41383607, 2025). "To further explore the effect of iNKT cells on macrophage subsets in chlamydial infection, we examined the amount of TNF-α protein in the macrophage subpopulations (AM, IM, and Mo/Mφ) of WT and iNKT KO mice on day 7 post-infection by intracellular cytokine staining." (PMID 38247825, 2024). "First, TNF-α may serve as a molecular target to reduce the clinically relevant reproductive pathologies that follow genital chlamydial infections." (PMID 23483844, 2013). "The role of TNF-α in chlamydial infections has been studied previously." (PMID 23483844, 2013). "Importantly, we have shown recently that TNF-α production contributes to upper GT pathology following vaginal chlamydial infection in mice." (PMID 23483844, 2013). "Interestingly, it sometimes happens, even in chlamydial infection, that in the presence of TLR2 or TLR4 deficiency in macrophages, there may be a decrease in TNF-α levels." (PMID 40647668, 2025). "CD8 T cells have conflicting roles in chlamydial infections, having been shown to cause immunopathology, predominantly through the production of TNFα, but in some cases also protection through atypical Chlamydia-specific cells secreting IL13 in addition to TNFα, IFNγ, and IL10." (PMID 36799886, 2023). "In contrast, the TLR3-/- mice secreted higher levels of IL-10, TNF-α and IFN-γ than wild-type mice at day 7 of infection, suggesting that TLR3 deficiency did not result in a global downregulation in synthesis of cytokines during early stages of chlamydial infection." (PMID 29624589, 2018). "However, the effects of TNF-α in the clearance of in vivo chlamydial infections are uncertain." (PMID 23483844, 2013). "Several important cytokines or antibodies in response to chlamydial infection in koalas have been identified: IFNγ, IL17, IL10, tumor necrosis factor alpha (TNFα), IgG, and IgA." (PMID 33102563, 2020). "LPS and TNF-α enhanced the expression and phosphorylation of cPLA2, while TNF-α neutralization during chlamydial infection impaired the process." (PMID 28634388, 2017). "Although high levels of variability was observed within each group, there was a significantly high expression (P<0.05) of TNFα and IL10 mRNA in animals with current chlamydial disease when compared to the remaining animals in the study." (PMID 23527290, 2013).
chlamydial infection (continued). "Reportedly T-cells co-expressing TNF-α/IL-2/IFN-γ elicit heightened protection against a genital chlamydial challenge, which provides additional evidence for the protective role of IFN-γ and IL-2 in chlamydial infections." (PMID 30374357, 2018). "The relative increase in production of important cytokines (TNF-α, IL-6, IL-2 and INF-γ) in the AHCC-fed group may lead to decreased chlamydia genital infection in the stress model." (PMID 27790645, 2015). "In summary, our data show that AHCC feeding to stressed mice results in (i) restoration of the functions of immune cells; (ii) reduced genital tract chlamydia shedding in AHCC-fed mice; and (iii) enhanced production of IFN-γ or TNF-α by T cell co-cultured with IL-1β producing monocytes." (PMID 27790645, 2015). "MCP-1, MIP-1α, and IL-8 secretion were comparable for low-dose chlamydial infection and stimulation with LPS, correlating with similar TNF-α secretion for the two stimuli, adding evidence to the finding that MCP-1, MIP-1α and IL-8 induction depend on TNF-α." (PMID 25488836, 2014). "In that study, we also showed that TNF-α was not required for clearance of primary genital chlamydial infections." (PMID 23483844, 2013). "Together, these results clearly indicate that the absence of TNF-α during the chlamydial infection process does not significantly affect IFN-γ production in the infected GT, or Chlamydia-specific IFN-γ and antibody production." (PMID 23483844, 2013). "However, a detailed evaluation of compensatory immunological parameters or the role of TNF-α production in clearance of secondary genital chlamydial infections was not conducted in that study." (PMID 23483844, 2013). "In preliminary studies comparing wild koalas with overt chlamydial disease, previous evidence of C. pecorum infection or no signs of C. pecorum infection, we revealed strong but variable expression of TNFα and IL10 in wild koalas with current signs of chlamydiosis." (PMID 23527290, 2013). "In natural infection settings, peripheral blood mononuclear cells (PBMCs) from koalas with active chlamydial disease have been found to have higher expression of IFN-γ and TNF-α than koalas with asymptomatic chlamydial infection or no chlamydial infection/disease." (PMID 33546104, 2021).
chronic hepatitis C (37 papers, 2005 to 2025). "In chronic hepatitis C, a decrease in LPS stimulated TNF production by monocytes was linked to poor disease outcome." (PMID 37877022, 2023). "TNF-α −308 G/A polymorphism was also reported to have a link to the pathogenesis and advancement of chronic hepatitis C." (PMID 34572300, 2021). "The TNF-α polymorphism in -308 and -238 positions of the TNF promoter has been involved in the variability of the histological severity of chronic hepatitis C infection." (PMID 23840511, 2013). "Chronic hepatitis C patients showed significant increase in soluble adhesion molecules, sICAM-1, sVCAM-1 as well as TNF-α." (PMID 35876981, 2023). "In chronic hepatitis C, the release of TNF-α and IL-1β by circulating mononuclear cells is greater than in healthy individuals." (PMID 31546715, 2019). "Whereas, other authors used mononuclear cells from patients with chronic hepatitis C to assess the effects of E2 and P4 on the production of TNF-α, IL-1β, IL-8, and macrophage chemotactic protein (MCP)-1." (PMID 31546715, 2019). "Serum ApN and tumor necrosis factor-α are independent predictors of liver steatosis, and ApN has additionally been found to be an independent predictor of response to chronic hepatitis C therapy." (PMID 26089882, 2015). "TNF-α is upregulated in patients with chronic hepatitis C (CHC) and this cytokine has been shown to interrupt insulin signaling via reduced-tyrosine phosphorylation of IRS-1 and decreased ability of IRS-1 to associate with the insulin receptor." (PMID 23049551, 2012). "The present study was conducted to evaluate blood apelin level changes among 73 chronic hepatitis C (CHC) Egyptian patients and if associated with body mass index (BMI), IR, and tumor necrosis factor-alpha (TNF-α)." (PMID 22007137, 2011). "As we here demonstrated CAHL induced by TNF-α, CAHL can express to some extent in the liver under chronic hepatitis C. We also show the association of CAHL with HCV replication." (PMID 21559518, 2011). "Activation of TNF-α has a pivotal role in the inflammatory process of chronic hepatitis C, and TNF-α levels correlate with the degree of inflammation." (PMID 21994721, 2010). "The patients with chronic hepatitis C exhibit an increased production of TNF-α, a cytokine that can produce oxidative stress by stimulating the generation of oxygen ROS." (PMID 16787540, 2006). "Intrahepatic levels of TNFα and IL-8 have been shown to be elevated in individuals with chronic hepatitis C infection." (PMID 16164755, 2005). "In another study, chronic hepatitis C patients presented elevated serum levels of IL-10, IFN-γ, IL-6, and IL-4, while IL-1, IL-2, IL17, IL-22, IL-13 TNF, IL-12p70, and IL-15 levels were lower in patients compared to healthy controls." (PMID 29977152, 2018). "Levels of inflammatory markers like IL-6, TNF-α and CRP are elevated in patients with chronic hepatitis C." (PMID 25438910, 2014). "This is an important finding since some studies have shown that the largest proportion of cellular infiltrate found in a liver with chronic hepatitis C is TH1 cells, such as IL-1b, IL-2, IL-6, IL-8, TNF-α and IFN." (PMID 22830036, 2012). "Indeed, accumulating evidence showed an increase in proinflammatory mediators, principally IL-6, IL-1β, interferon-γ (IFN-γ), and TNF-α in depressed individuals and in patients developing depressive symptoms after therapeutic treatments, such as IFN-α therapy for chronic hepatitis C." (PMID 35886944, 2022). "Furthermore, a potential hepato-protective effect of TNF-α induced by increasing hepatocyte regeneration and decreasing apoptosis has been observed in a transgenic mouse model of chronic hepatitis C while treatment with anti-TNF-α blocked the anti-apoptotic and regenerative effects induced by TNF-α." (PMID 22535279, 2012).
chronic hepatitis C (continued). "In addition, it has been shown that HCV-positive hemodialysis patients had a blunted TNF-alpha response and failed to increase the stimulated IFN-gamma and IL-12 production compared with chronic hepatitis C patients without renal disease." (PMID 16842626, 2006).
colorectal tumor (37 papers, 2012 to 2025). "The AOM/DSS treated mice developed multiple colorectal tumors in the colon tissues, suggesting that TNF-α and IL-6 may be associated with tumor formation." (PMID 31694526, 2019). "Elevated cytokines such as IL-6 and TNF-α promote colorectal tumor initiation and progression via inflammatory and proliferative mechanisms." (PMID 40399803, 2025). "In the AOM/DSS-induced orthotopic CRC model, KGM-PTX/CSM significantly inhibited colorectal tumor growth, improved survival rates, and suppressed inflammatory cytokine expression (TNF-α, IL-1β, IL-6, and IL-10) in serum and colorectal tissues." (PMID 40528838, 2025). "Inactivation of PSMD5 was shown to promote colorectal tumor progression, TNF-α increases PSMD5 expression through NFκB." (PMID 37349676, 2023). "Pre-treatment levels of IL-6, TNF-α, and CRP were significantly associated with increased phenotypic frailty in colorectal tumors." (PMID 37213604, 2023). "Aggravation of colorectal tumors; induction of inflammatory cytokines and pathways (TNF-α, IL-1β, IL-6, IL-10)." (PMID 35893902, 2022). "Increased TNFα levels are linked to increased leukocyte infiltration and tumor formation and upregulation of TNFα levels are usually detected in colorectal neoplasms, and in animal models of CRC." (PMID 31540047, 2019). "TNF-α and IL-6 are core cytokines in the colorectal tumor promotion by activating NF-κB signaling pathways and STAT3." (PMID 30157754, 2018). "Having demonstrated the link between TLR4/NF-κB and TNF-α/NOS2 induction in colorectal tumors, we focused our attention to elucidate the immunomodulatory effect of all-trans retinoic acid in NOS2 and TNF-α expression in inflamed colonic mucosa cultures." (PMID 28408791, 2017). "TNFα is produced in colorectal tumors by infiltrating macrophages, and higher TNFα expression is correlated with increased tumor diameter." (PMID 23866118, 2013). "Human colorectal tumors contain CD11c+ macrophage-like cells that produce TNFα, and Th17 cells that produce IL-17; thus, the two cytokines are both expressed in colorectal tumors." (PMID 23866118, 2013). "Moreover, IL-17 secreting CD4+ T cells infiltrated in colorectal tumors can coproduce TNF-α and IL-10." (PMID 33327620, 2020). "Furthermore, IL-23 induces γδT17 cells to secrete IL-17, IL-8, tumor necrosis factor α, and granulocyte-macrophage colony-stimulating factor, consequently recruiting and activating MDSCs in colorectal tumors." (PMID 32063899, 2019). "Interestingly, we found that despite being highly infiltrated by potentially immunosuppressive CD39+ Treg cells, colorectal tumors contain significant numbers of pro-inflammatory IL-17 and TNF-α secreting T cells." (PMID 27014625, 2016). "In the present study, we investigated the role of 1,25D3, TNFα, and IL-6 on the transcriptional and translational activation of the CaSR in two cell lines representing a highly differentiated and a moderately differentiated colorectal tumor." (PMID 24176760, 2014). "Moreover, increased TNFα expression is correlated with increased diameter and extent of primary tumors, and studies of mouse models have indicated that IL-23/IL-17 signaling plays a key role in colorectal tumor development." (PMID 23866118, 2013). "In CT26 colorectal tumor-bearing mice, a single round of PDT with porphyrin-lipid photosensitizer incorporated into a polymeric core–shell nanoparticle increased serum TNF-α, IFNγ, and IL-2 the day after PDT." (PMID 36405502, 2021). "TCP-1/TNFα and TCP-1/IFNγ recombinant proteins were prepared and i.v. injected to study the in vivo anticancer effect in orthotopic colorectal tumor model." (PMID 27342639, 2016). "In this study, we extended to study the effect of TCP-1/TNFα and TCP-1/IFNγ either alone or in combination in orthotopic colorectal tumor model in immune-competent mice." (PMID 27342639, 2016).
colorectal tumor (continued). "In the current study, the antitumor effect of TCP-1/TNFα and TCP-1/IFNγ alone or in combination was studied in orthotopic colorectal tumor model." (PMID 27342639, 2016). "Previous studies evaluating the effect of PN enriched with ω3 LE on the immune response of patients with gastric or colorectal tumors found significant differences between groups in reducing the inflammatory response, measured by parameters like IL-6, CRP, and TNF-α." (PMID 38201870, 2023). "Entolimod did not interfere with the antitumor activity of TNF in mouse hepatocellular and colorectal tumor models." (PMID 32027657, 2020). "Using the murine Hepa 1–6 and BNL HCC tumor models along with the highly aggressive CT26 colorectal tumor model, we determined that entolimod’s protective activity against TNF toxicity is limited to normal tissues (not tumors), even with D-GalN sensitization." (PMID 32027657, 2020). "Targeted delivery of TNFα by TCP-1 peptide displayed more potent antitumor activity than unconjugated TNFα by inducing more apoptosis and destructing neovasculature in orthotopic colorectal tumors at 24 h with the dose 5 μg/mouse." (PMID 27342639, 2016). "Here, we explored the antitumor effect of targeted TNFα or IFNγ in CRC through using fusion protein of TNFα or IFNγ with TCP-1 peptide, a novel ligand which can specifically bind to the vasculature of orthotopic colorectal tumors." (PMID 27342639, 2016). "TNF-α also has angiogenic effects; thus, the Th17 cells that coproduce TNF-α, but not IFN-γ, which we have identified as being enriched in colorectal tumor tissue, may be particularly effective at inducing angiogenesis and thereby promoting tumor growth." (PMID 27014625, 2016).
metastatic melanoma (37 papers, 2012 to 2026). A melanoma that has spread from its primary site to another anatomic site. "In patients with metastatic melanoma treated with PD-1, TNF expression is increased, and there is a strong positive correlation between TNF and PDCD1LG1 (encoding PD-L1)." (PMID 32000802, 2020). "In B16F10 metastatic melanoma mice, TNF, through its binding to TNFR2, induced Treg proliferation, resulting in the escape of tumor cells from immune surveillance." (PMID 38474115, 2024). "CTLA-4 blockade, by ipilimumab, introduced in recent years in the treatment of metastatic melanoma, NSCLC and other cancers, incurs severe adverse events associated with toxicity, as observed by the high levels of TNF-α." (PMID 36355837, 2022). "Overall this study introduces a novel anti-tumor role of pulmonary ILC2s in the context of metastatic melanoma through the production of TNF-α." (PMID 34531874, 2021). "It has been indicated that anti-CTLA-4 administration can potentiate the immune responses of NY-ESO-1 antigen-specific B cell and T cells through augmented production of MIP-1β, IFN-γ, and TNF-α in patients suffering from metastatic melanoma." (PMID 32902664, 2021). "Here, we found that high baseline levels of MCP1 and TNFα were predictors of superior PFS in metastatic melanoma patients treated with checkpoint inhibitors." (PMID 32486146, 2020). "In summary, in our cohort, undetectable ctDNA after 6–8 weeks of therapy and high baseline levels of MCP1 and TNFα are all individual predictors of superior PFS in metastatic melanoma patients treated with first-line checkpoint inhibitors." (PMID 32486146, 2020). "Recombinant TNFα was shown to induce cancer cell senescence when combined with interferon-γ treatment, and was demonstrated to induce tumor cell death in metastatic melanoma via isolated limb perfusion." (PMID 30626869, 2019). "TNF has proved to have an effect on metastatic melanoma treatment and unresectable soft tissue therapies." (PMID 31381571, 2019). "An ongoing phase I clinical trial (NCT03293784) is evaluating the safety and tolerability of treating metastatic melanoma with ICIs combined with either infliximab or certolizumab, a similar anti-TNFα agent." (PMID 31439050, 2019). "In TICIMEL, which started in December 2017, 30 patients with metastatic melanoma are for the first time simultaneously treated with TNF blocking antibodies (Infliximab or Certolizumab), and ICI (Nivolumab and Ipilimumab)." (PMID 31417576, 2019). "An ongoing phase 1b clinical trial (NCT03293784) will evaluate the safety and tolerance of the combination of immune checkpoint inhibitors and anti-TNF in metastatic melanoma patients." (PMID 29273790, 2017). "The TNF effect on TIM-3 expression was dose-dependent in a distinct autologous co-culture experiment using TILs from another metastatic melanoma patient." (PMID 29273790, 2017). "In patients with recurrent metastatic melanoma in the limb, high doses of the cytotoxic drug melphalan and recently, tumor necrosis factor (TNF) and IFNγ are given to the patient via isolated limb perfusion to reduce systemic toxicity." (PMID 29276510, 2017). "A prospective Phase Ib trial that enrolled 14 patients with advanced and/or metastatic melanoma (stage IIIc/IV) combined ICI with TNF blockade (infliximab or certolizumab) and demonstrated favorable tumor outcomes: seven of seven evaluable patients achieved objective response with 4 CRs and 3 PRs." (PMID 39737191, 2024). "Indeed, the metastatic melanoma cell line 451Lu, when treated with TNF, also underwent a dedifferentiation process, as evidenced by RT-qPCR on a set of 5 transcripts representative of the differentiation status." (PMID 39136013, 2024).